EGFL6 (EGF like domain multiple 6)
Description:
May bind integrin alpha-8/beta-1 and play a role in hair follicle morphogenesis. Promotes matrix assembly (By similarity).
Synonyms: MAEG; W80
Tractability: Antibody: UniProt places it where antibodies can reach, with medium confidence; UniProt predicts a signal peptide or a membrane-spanning region; its Gene Ontology location is reachable by antibodies, with medium confidence.
Gene: Protein-coding gene on chromosome X (13,569,601 to 13,633,575, forward strand). Ensembl gene ENSG00000198759.
Subcellular location: Secreted, extracellular space, extracellular matrix, basement membrane
Gene Ontology:
Molecular function: protein binding; integrin binding; calcium ion binding
Cellular component: extracellular region; basement membrane; extracellular matrix; membrane
Homologues: Orthologues: chimpanzee EGFL6 (99% identical), macaque EGFL6 (95% identical), guinea pig EGFL6 (82% identical), rat Egfl6 (80% identical), mouse Egfl6 (78% identical), pig EGFL6 (76% identical), tropical clawed frog egfl6 (54% identical), zebrafish egfl6 (43% identical). Paralogues in human: NPNT (37% identical).
Diseases named in the same sentence as EGFL6 in open-access papers:
EGFL6 is named in the same sentence as 47 diseases in open-access papers, as found by Europe PMC text mining. Sharing a sentence is not in itself a finding about the gene and the disease. The quoted sentences say what the papers report.
ovarian carcinoma (22 papers, 2012 to 2025). A malignant neoplasm originating from the surface ovarian epithelium. "The poor performance of EGFL6 in various cancers, including nasopharyngeal carcinoma, lung adenocarcinoma, ovarian cancer, etc. may be associated with its remarkable immunosuppressive effect in the tumor immune microenvironment." (PMID 33391349, 2020). "We demonstrated another association of EGFL6 with the pathway downstream to miR-6086, which may serve as a unique biomarker for ovarian cancer therapy." (PMID 32393810, 2020). "For example, in ovarian cancer, overexpression of EGFL6 was associated with drug resistance." (PMID 33391349, 2020). "We observed an intricate association of the OC2/VEGFA/EGFL6 axis which could promote angiogenesis and tumorigenesis in ovarian cancer, together with other angiogenic factors." (PMID 32393810, 2020). "Alterations of EGFL6 associated with metastasis of ovarian cancer." (PMID 32315343, 2020). "However, the mechanism connecting EGFL6 and the cascade signal pathway associated with ovarian cancer cell apoptosis requires further investigation." (PMID 32983976, 2020). "In syngeneic mouse models of ovarian cancer (OvCa), tumor expression of Egfl6 increased the intratumoral accumulation of polymorphonuclear (PMN) MDSCs and TAMs and their expression of immunosuppressive factors, including CXCL2, IL-10, and PD-L1." (PMID 39312740, 2024). "EGFL6 is a protein known to be highly expressed in ovarian cancer and proposed to play a key role in promoting tumor angiogenesis." (PMID 36497228, 2022). "It has been reported that EGFL6 is involved in the development of a variety of tumors, such as ovarian cancer and colon cancer; however, its role in the regulation of osteogenic differentiation of ADSCs is rarely studied." (PMID 35220882, 2022). "The low expression of ANP32E, STAT1, GPRC5A, EGFL6, and PMP22 was positively associated with overall survival time of ovarian cancer." (PMID 34660776, 2021). "Combining TCGA ovarian cancer dataset, we identified differentially expressed marker genes that were significantly associated with prognosis of ovarian cancer, including ANP32E, STAT1, GPRC5A, EGFL6, PMP22, FBXO21, and CYB5R3." (PMID 34660776, 2021). "We found that the expression levels of STAT1, ANP32E, GPRC5A, and EGFL6 were all significantly higher in ovarian cancer tissues compared with normal tissues." (PMID 34660776, 2021). "A previous study has found that EGFL6 is upregulated in drug-resistant ovarian cancer cell lines using microarray analysis." (PMID 34660776, 2021). "The role of EGFL6 in carcinogenesis has been investigated in ovarian cancer but the mechanism is unclear." (PMID 32983976, 2020). "Since then, EGFL6 was reported to be overexpressed in tumors and in abnormal microenvironments such as the bone local environment and ovarian cancer." (PMID 32008086, 2020). "The results showed that EGFL6 was expressed in all the ovarian cancer cell lines but with variations." (PMID 32983976, 2020). "Compared to EGFL6 levels in tumors, it was found EGFL6 was overexpressed in lung cancer, colorectal cancer, breast cancer, nasopharyngeal cancer, ovarian cancer, and hepatocellular carcinoma." (PMID 32008086, 2020). "Moreover, we found that deletion of EGFL6 could decrease the expression of Bcl-2 and increase the expression of Bax and Caspase-8, which could activate the Caspase-3 signal pathway and cause apoptosis of ovarian cancer cells." (PMID 32983976, 2020). "Next, our analysis identified that OC2 and EGFL6 were the direct targets of miR-6086 and we further demonstrated the relationship between miR-6086 and the OC2/VEGFA/EGFL6 axis in ovarian cancer." (PMID 32393810, 2020). "EGFL6 protein is highly expressed in ovarian cancer and has been proposed to play an important role in promoting tumor angiogenesis." (PMID 32983976, 2020).
ovarian carcinoma (continued). "Taken together, these results indicated that a tight regulatory network of the OC2/VEGFA/EGFL6 axis functioned downstream to miR-6086 in ovarian cancer." (PMID 32393810, 2020). "EGFL6 is highly expressed in ovarian cancer tissues, and participates in the development of ovarian cancer by stimulating ovarian tumor angiogenesis 39,40." (PMID 32624687, 2020). "Considering the multiple mechanisms proposed in different cancers, the role of EGFL6 in tumor angiogenesis and progression of ovarian cancer requires further investigation." (PMID 32983976, 2020). "In conclusion, EGFL6 is an oncogenic gene involved in multiple pathways influencing ovarian cancer cell proliferation, metastasis, and angiogenesis." (PMID 32983976, 2020). "In the nude mouse model of ovarian cancer, knockout of EGFL6 remarkably inhibited tumor growth and angiogenesis." (PMID 32983976, 2020). "Compared to normal ovaries, EGFL6 mRNA was significantly elevated in ovarian cancer histology and induced ovarian cancer cell proliferation." (PMID 32231122, 2020). "The use of EGFL6 monoclonal antibody in ovarian cancer tumor model significantly reduces tumor angiogenesis." (PMID 32624687, 2020). "It found the levels in healthy controls ranged from 0 to 48 pg/ml, while the levels in patients with various tumors ranged from 0 to 1364 pg/ml, of which the level of EGFL6 in ovarian cancer was highest (616 pg/ml)." (PMID 32008086, 2020). "Patients with benign meningiomas and ovarian cancers had significantly higher serum EGFL6 levels than those with other intra- and extra-cranial tumors." (PMID 23285163, 2012). "We also found that EGFL6 gene was expressed at a low level in all other tumors except ovarian cancer." (PMID 23285163, 2012). "ELISA analysis showed that patients with benign meningiomas and ovarian cancers had the highest serum levels of EGFL6 (mean concentration: 672 pg/ml for benign meningiomas, and 616 pg/ml for ovarian cancers)." (PMID 23285163, 2012). "EGFL6 gene was also highly expressed in ovarian cancer, but expressed lowly in other investigated tumors." (PMID 23285163, 2012). "Furthermore, marker genes, STAT1, ANP32E, GPRC5A, and EGFL6, were highly expressed in ovarian cancer, while PMP22, FBXO21, and CYB5R3 were lowly expressed in ovarian cancer." (PMID 34660776, 2021). "MiR-6086 suppressed ovarian cancer angiogenesis via regulating the OC2/VEGFA/EGFL6 axis." (PMID 34302635, 2021). "EGFL6, a stem cell regulator expressed in ovarian tumor cells and vasculature, may induce the growth and metastasis of ovarian cancer." (PMID 34660776, 2021). "Moreover, our functional analysis identified miR-6086 as a master regulator of tumorigenesis and angiogenesis in ovarian cancer by downregulating the OC2/VEGFA/EGFL6 axis." (PMID 32393810, 2020). "Similarly, to investigate the role of EGFL6 in ovarian cancer progression and angiogenesis, we decreased its expression by over 70% in Skov3 with the recombinant plasmid pGPU6-GFP-Neo-siEGFL6." (PMID 32393810, 2020). "However, the molecular mechanism of EGFL6 function in the tumorigenesis of ovarian cancer needs further investigation." (PMID 32983976, 2020). "Indeed, EGFL6 regulates the asymmetric division, maintenance and metastasis of ovarian cancer stem-like cells." (PMID 32393810, 2020). "Therefore, there was an inverse relationship between miR-6086 and the OC2/EGFL6 axis both in ovarian cancer cell lines and tissues." (PMID 32393810, 2020). "We also found that EGFL6 could promote metastasis through the EMT signal pathway in ovarian cancer tumor." (PMID 32983976, 2020). "Anti-EGFL6 can completely eliminate ovarian cancer cells from diffusing into the blood of the ovary, suggesting that EGFL6 may play a key role in the ovarian microenvironment." (PMID 32624687, 2020). "On the other hand, knockout of EGFL6 in ovarian cancer cells could reduce the phosphorylation level of Erk, Akt, and mTOR." (PMID 32983976, 2020).
ovarian carcinoma (continued). "Taken together, our results reveal that miR-6086 can suppress the angiogenesis networks in ovarian cancer by down-regulating the OC2/VEGFA/EGFL6 axis, directly or indirectly, which may provide potential targets for tumor therapeutics." (PMID 32393810, 2020). "In this study, suppressing the expression of OC2 or EGFL6 could inhibit tumorigenesis, angiogenesis and relevant factor secretion in ovarian cancer." (PMID 32393810, 2020). "EGFL6 neutralizing antibody inhibits the growth and metastasis of ovarian cancer cells." (PMID 32624687, 2020). "In this study, we found that the knockout of EGFL6 could affect the signaling pathways for ovarian cancer tumorigenesis, by activation of the integrin/Akt/mTOR and MAPK/Erk pathways." (PMID 32983976, 2020). "Our results indicated that the knockout of the EGFL6 gene could inhibit EMT in ovarian cancer cells by upregulating the expression of E-cadherin and downregulating the expression of N-cadherin, MMP2, MMP9, and Vimentin." (PMID 32983976, 2020). "Interestingly, the average expression of OC2 and EGFL6 was significantly higher in ovarian cancer cell lines and tissues than the normal samples and these two factors were observed in obviously positive correlation." (PMID 32393810, 2020). "To determine if our empirical sampling based algorithm was able to accurately predict the effects caused by treatment with EGFL6, we ran simulation experiments for SKOV3 and primary ovarian cancer cells based on single cell observations and compared the predictions to bulk growth." (PMID 29340046, 2017). "EGFL6 mRNA levels were very high in ovarian cancer, which were comparable with benign meningioma." (PMID 23285163, 2012). "Interestingly, EGFL6 mRNA was also found with a high level in ovarian cancer, comparable to that in benign meningioma." (PMID 23285163, 2012). "However, its expression is upregulated in ovarian cancer, marking Egfl6 as an interesting candidate for ovarian differentiation." (PMID 22844512, 2012). "Importantly, patients with ovarian cancer also had high serum EGFL6 levels (mean concentration: 616 pg/ml)." (PMID 23285163, 2012). "Furthermore, EGFL6 has been shown to be expressed in some cases of hyperplasia, such as ovarian cancer and meningioma, and it is particularly highly expressed in tumour-associated endothelial cells compared to other endothelial cells and is involved in tumour angiogenesis." (PMID 35457174, 2022). "Bai S’s study had also proven that EGFL6 promotes the asymmetric division of cancer stem-like cells in ovarian cancer, consistent with this research’s result that EGFL6 could keep the cell stemness by regulating the expression of cancer stem cell associated genes, POU5F1, NANOG, and LIN28." (PMID 33726836, 2021). "Therefore, understanding the function of EGFL6 in ovarian cancer could have potential implications for diagnosis and therapy." (PMID 32983976, 2020). "Thus, the results of this study indicated that EGFL6 could regulate cell proliferation, migration, and angiogenesis in ovarian cancer cells by regulating the FGF-2/PDGFB signaling pathway." (PMID 32983976, 2020). "EGFL6 might serve as a therapeutic target and prognostic marker for ovarian cancer." (PMID 32983976, 2020). "Therefore, the inhibition of EGFL6 could suppressed tumorigenesis and angiogenesis in ovarian cancer." (PMID 32393810, 2020). "Interestingly, the authors also found that vascular EGFL6 expression enhances the distant metastasis of ovarian cancer cells through the hematogenous route, whereas an EGFL6 blockade reduces the hematogenous spread of ovarian cancer cells to distant parenchymal organs." (PMID 31261739, 2019). "EGFL6 has been shown to promote asymmetric division, maintenance, and metastasis of ALDH+ ovarian cancer cells." (PMID 40868176, 2025).
ovarian carcinoma (continued). "EGFL6 promotes the growth and metastasis of ovarian cancer by promoting the migration and asymmetric division of cancer stem cells (CSC) in ovarian cancer, Bai and colleagues 39 found that EGFL6 is expressed in both tumor cells and vascular cells." (PMID 32624687, 2020). "To investigate the role of miR-6086 in ovarian cancer, we selected Skov3 with low miR-6086 and high expression of the OC2/EGFL6 axis for subsequent experiments, while Caov3 served as a control." (PMID 32393810, 2020). "High expression of GJB2, S100A2, SPOCK2, TGM1or EPS8 indicated a poor OS of patients with ovarian cancer, whereas ovarian cancer patients with higher expression of ADAMDEC1, CHEK1, EGFL6, FAM181A, FOXA2, LYPD1, PART1 or XPR1 possessed better OS." (PMID 31794425, 2019). "In ovarian cancers, EGFL6, a stem cell regulatory factor expressed in ovarian tumor cells, regulates SHP2 and its concomitant activation of ERK and eventually promotes ALDH+ ovarian cancer stem-like cells migration and asymmetric division." (PMID 29983715, 2018). "KEGG enrichment analysis showed that knockdown of EGFL6 could affect MAPK signaling pathway, TNF, ECM, and Jak-STAT signaling pathways in ovarian cancer cells." (PMID 32983976, 2020). "In our study, we found that EGFL6 was highly expressed in ovarian cancer tissues from patients, regardless of subtypes of the tumor." (PMID 32983976, 2020). "We repeated the microfluidic growth assay with ALHD+ and ALDH(-) SKOV3 cells or primary ovarian cancer cells in the presence of absence of EGFL6." (PMID 29340046, 2017). "Besides benign meningioma and ovarian cancer, MAEG (EGFL6) gene was also found expressed in several fetal tissues including lung, kidney, dermatome and dermatome derivatives." (PMID 23285163, 2012). "In that study, EGFL6 showed limited or no expression in normal tissues by qRT-PCR and analysis of a publicly available gene expression profile data set, but was expressed at a high level in ovarian cancer." (PMID 23285163, 2012). "The expression of EGFL6 was detected in a panel of human ovarian cancer cells (CAOV3, COV-362, COV-504, EFO-27, ES-2, OV-90, SKOV3, and TOV-21G), and EGFL6 expression in HUVECs served as a negative control." (PMID 32983976, 2020).
Obesity (11 papers, 2020 to 2024). Accumulation of substantial excess body fat. "Specifically, the EGFL6 gene is associated with obesity-related inflammation in children, and the DMD gene with muscle inflammation." (PMID 39844836, 2024). "EGFL6 expression, which encodes an epidermal growth factor found to be enhanced in obesity and alters insulin action, was increased by 8.5-fold." (PMID 32826922, 2020). "The expression of EGFL6 in subcutaneous adipose tissue increases significantly with obesity and decreases after weight loss." (PMID 32624687, 2020). "Finally, we investigated whether the obesity-associated increase in EGFL6 expression in AT is reversible by analysing 43 paired AT samples before and after lifestyle-induced weight loss in well-characterised male individuals." (PMID 35457174, 2022). "Egfl6, a growth factor upregulated in obesity and involved in AT growth in humans, was higher expressed in females than males." (PMID 34997206, 2022). "In summary, adipocyte EGFL6 expression was related to obesity, AT dysfunction, and early signs of metabolic disease in children and obesity-related alterations in EGFL6 expression can be reversed by weight loss." (PMID 35457174, 2022). "Although no target sites for Notch3 have been identified within the genetic sequence of Egfl6, a special functional connection has been evidenced between both genes in the context of obesity and angiogenesis." (PMID 32275707, 2020). "Oberauer and colleagues 27 found that EGFL6 is up-regulated in human obesity and promotes proliferation of adipose tissue-derived stromal vascular cells." (PMID 32624687, 2020). "Higher expression of ANGPT2, HIF-1a, EGFL6, several MMP genes, and GDF15 was observed in individuals living with obesity (p ≤ 0.008)." (PMID 38024342, 2023). "When analysing isolated adipocytes and SVF cells derived from subcutaneous AT of children, we detected significantly increased expression of EGFL6 in adipocytes compared to SVF cells in lean children, which was even more elevated in children with obesity." (PMID 35457174, 2022). "Higher expression of angiopoietin-2 (ANGPT2), HIF-1α, EGF like domain multiple 6 (EGFL6), several MMP genes, and growth/differentiation factor-15 (GDF15) was observed in individuals living with obesity (P ≤ 0.008)." (PMID 35958557, 2022).